IL6 (interleukin 6)
Diseases named in the same sentence as IL6 in open-access papers (continued):
Sharing a sentence is not in itself a finding about the gene and the disease.
pulmonary TB (continued). "Cytokines such as IL-1, sIL-2R, TNF-α, IL-5, IL-6, and IFN-γ play important roles in pulmonary tuberculosis patients, and their elevated levels may be associated with disease severity and inflammatory status." (PMID 39432654, 2024). "Our research showed that the retreatment group had a considerable rise in IL-6 concentrations When juxtaposed with the initial treatment and control groups, suggesting that the development and outcome of pulmonary TB may be related to its overexpression." (PMID 38650928, 2024). "Furthermore, IL-6 has shown potential as a biomarker for a triage test for active pulmonary TB in adults with persistent cough and as a biomarker for monitoring treatment efficacy of active TB disease." (PMID 34943175, 2021). "Furthermore, IL-6 increased inflammatory cytokine production by T lymphocytes in pulmonary tuberculosis patients with T2DM." (PMID 27783671, 2016). "We found that either specific antigen could stimulate PBMCs from pulmonary tuberculosis patients to produce higher levels of IL-6 and IL-9 than PBMCs from HDs." (PMID 23028695, 2012). "Similarly, we found a significant increase in the plasma levels of IL-6 and IL-9 in patients with active pulmonary tuberculosis and tuberculous pleurisy." (PMID 23028695, 2012). "The aim of our study was to investigate whether IL6–174 G>C SNP and IL17A -197 G>A polymorphism and additional cytokine genes involved in immune response to MTB (IL2, IL4, IL10, IFNG and TNF) are associated with genetic susceptibility to pulmonary TB (PTB)." (PMID 26840977, 2016). "Some studies have found that the levels of IL-6 and TNF-α inflammatory cells increase in pulmonary tuberculosis, which is similar to the conclusion of this study." (PMID 39258673, 2024). "Heterogeneity was assessed for biomarkers that reported sensitivity and specificity in at least four studies for adult pulmonary TB (CRP, HO-1, IFN-γ, IL-6, IP-10, MIG, TNF, and VEGF)." (PMID 39445833, 2024). "The classical cytokines such as IL-2, TNF-α, IL-6 and IFN-γ, have been reported to correlate with disease activity during active pulmonary TB." (PMID 23626814, 2013). "It was reported that the synthesis of cytokines in pulmonary TB with DM patients showed significant changes compared to pulmonary TB without DM, such as IL-2, IL-6, IL-17, TNF-α and IFN-γ." (PMID 38027218, 2023). "Similarly, an earlier study has shown that treatment with a PDE4i such as roflumilast and rolipram controlled the neutrophil recruitment by reducing TNF-α, IL-6, CXCL1, and CXCL2/3 in a rabbit model of pulmonary TB." (PMID 37854602, 2023). "Men had higher IL6, IL8, and TNFα levels than women, and female patients’ and healthy controls’ IL8 and TNFα levels were similar, supporting the notion that men are the main contributors to the highly pro-inflammatory profile observed in pulmonary TB patients." (PMID 35454079, 2022). "It was reported that the synthesis of cytokines in pulmonary TB with DM patients shown significant changes compared to pulmonary TB without DM, such as IL-2, IL-6, IL-17, TNF-α and IFN-γ." (PMID 34134685, 2021). "Statistical analysis was performed on the release of IL-6 and IFN-γ induced by antigen E6C10 in PBMC of patients with bacterial-negative pulmonary tuberculosis, patients with bacterial-positive pulmonary tuberculosis and healthy volunteers to confirm whether there was any difference." (PMID 37077246, 2023). "Further,we analyzed the different genera present in pulmonary TB patients with and without injury at T2 and their correlations with the inflammatory factors TNF-α, IL-6, and IL-1β." (PMID 40129950, 2025).
amyloidosis (46 papers, 2013 to 2025). A disorder characterized by the localized or diffuse accumulation of amyloid protein in various anatomic sites. "Its association with amyloidosis is believed to occur secondary to the production of IL-6 by its hyperplastic lymph nodes." (PMID 23431491, 2013). "Regarding the mechanism of inflammation in amyloidosis, pro-inflammatory cytokines such as IL-1β, IL-6, and TNF-α are associated with the formation of amyloid plaques, and these cytokines are proposed to trigger inflammatory responses and promote tissue damage." (PMID 40571902, 2025). "This fact suggests that IL-6 may play a causative role in the increase in amyloid plaque formation and subsequent neuronal damage." (PMID 39860337, 2025). "It has also been suggested that inhibition of IL-6 may have a therapeutic effect on amyloidosis, which is frequently associated with these chronic inflammatory diseases." (PMID 35958618, 2022). "In addition, both IL-1β and IL-6 are also known as key mediators in chronic inflammation and are associated with long-term hemodialysis complications such as erythropoietin hyporesponsiveness, cardiovascular morbidities and amyloidosis-related bone disease." (PMID 29069222, 2017). "Importantly, while previous studies have reported associations between elevated IL-6 levels and adverse outcomes in amyloidosis, our findings may have been constrained by the limited sample size, emphasizing the need for validation in larger, adequately powered cohorts." (PMID 41007815, 2025). "A chronic state of inflammation caused by cytokines like IL-6, IL-18, and TNF-α represents a major link to the formation of increased amyloid plaques and tau tangles." (PMID 41280310, 2025). "There have been suggestions that elevated levels of serum IL-6 are related to higher levels of amyloid in the brain." (PMID 41280310, 2025). "Tocilizumab (anti–IL-6 agent) has been successful in controlling disease activity and improving proteinuria in patients with FMF-associated amyloidosis and also in few TRAPS and HIDS/MKD patients resistant to anti-TNF and/or anti–IL-1 agents." (PMID 32655539, 2020). "Tocilizumab was also used to treat amyloidosis secondary to different rheumatic inflammatory diseases by down-regulating IL-6 and therefore reducing sera levels of SAA." (PMID 29617422, 2018). "Recently beneficial effect of TCZ, an anti IL-6 agent in the treatment of amyloidosis secondary to JIA has been reported." (PMID 28558744, 2017). "In amyloidosis, bacterial components such as LPS and metabolites, formed by bacteria such as SCFAs, and TMAO have been associated with amyloid deposits and pro-inflammatory cytokines (e.g., interleukin-1β (IL-1β) and IL-6)." (PMID 39857728, 2025). "Moreover, lowering IL-6 levels restores cognitive function and decreases amyloid load in an AD animal model." (PMID 41373742, 2025). "Likewise, a study assessed the potential association between IL-6 (−174G/C) polymorphism and amyloidosis in 156 FMF adult patients, of whom 80 had amyloidosis." (PMID 39132307, 2024). "IL-6 is a pleiotropic cytokine involved in other biological processes in the central nervous system, including neuronal development and differentiation, neurogenesis, and amyloid plaque clearance." (PMID 39251589, 2024). "Only limited data on IL-6 inhibition in amyloidosis are available." (PMID 36260501, 2022). "It will also add to the understanding of the potential efficacy of IL-6 inhibitors on secondary amyloidosis, which may dramatically improve the prognoses of individuals with FMF." (PMID 30594222, 2018). "In the last decade, tocilizumab (an anti-IL-6 biological) has been reported to successfully suppress SAA levels in polyarteritis nodosa and RA and was proven successful in regulating AA amyloidosis itself, even causing regression of amyloid plaques." (PMID 29617422, 2018).
amyloidosis (continued). "To assess whether the increased amyloid plaque burden resulted in an exacerbation of pro-inflammatory responses, we measured levels of the inflammation-associated molecules CXCL1, CCL3, IL-33, TNFα, IL-6, and IL-1β by multiplexed MSD ELISA." (PMID 32943069, 2020). "In this regard, further studies are recommended in order to precisely evaluate the efficacy and safety of anti-TNF-α and anti-IL-6 drugs in the management of FMF severity and complications, mainly amyloidosis, among children." (PMID 39132307, 2024). "The production of the precursor to SAA is the main step in the pathogenesis of amyloidosis, which is produced by inflammatory signals, IL-1β, tumor necrosis factor (TNF)-α, and IL-6." (PMID 27590627, 2016). "IL-6 and TNF-α, which are representative pro-inflammatory cytokines, were found to be induced in reactive astrocytes surrounding beta-amyloid deposits detected in 14-month-old Tg2576 mice." (PMID 24586443, 2014). "There are few reports on the effect of anti-TNF and anti-IL-6 treatment on SAA concentration, dealing mostly with patients with amyloidosis, secondary to RA." (PMID 25525305, 2014). "We have previously shown that plasma concentration of IL-6 is elevated in amyloid-negative RHI compared to controls and AD." (PMID 40524252, 2025). "Il6 mRNA levels in quadriceps were dramatically upregulated more than 5-fold by IT compared to sedentary mice, regardless of influence by AApoAII amyloidosis, whereas IL6 mRNA levels in the CT groups were elevated ∼2-fold." (PMID 35099007, 2022). "Taken together, there is a possibility that the treatment with PCO causes elevation of HDL-C and enhancement of HDL functionality to induce the reduction of oxidized species (4-HNE and iNOS), inflammatory cytokines (IL-1β, IL-6, and TNF-α), and amyloid plaque size." (PMID 34439569, 2021). "INS, IL6 increases while APOE and APOA1 decrease the prediction of amyloidosis." (PMID 32753925, 2020). "The levels of Tnfa and Il6 tended to be less than those of the AL groups, but all levels of the CR groups were lower regardless of the amyloidosis-induction." (PMID 28225824, 2017). "Inflammatory cytokines, including interleukin (IL) 1β, IL6 and tumor necrosis factor-alpha (TNF-α), are involved in local inflammation triggered by amyloid plaque deposition and may induce neurotoxicity when produced chronically, favoring the generation of Aβ peptides." (PMID 32283734, 2020).
anxiety disorder (46 papers, 2011 to 2026). A category of psychiatric disorders which are characterized by anxious feelings or fear often accompanied by physical symptoms associated with anxiety. "The prospective Whitehall II cohort study reported that over 12 years, participants with a high IL-6 level at baseline had a higher risk of depressive and anxiety disorders at follow-up than those with a low IL-6 level at baseline." (PMID 35558424, 2022). "Afterbasic adjustment, higher basal levels of CRP and IL-6 were associated with thepresence of current depressive/anxiety disorder." (PMID 27244234, 2016). "Pro-inflammatory cytokines such as TNF-α, IL-17, and IL-6 have been variably associated with mood and anxiety disorders; however, published data remain inconsistent, with reports of both upregulation and downregulation depending on disease context, population, and methodology." (PMID 41598638, 2026). "However, authors of a recent population-based study were unable to replicate associations between high levels of IL-6 and anxiety disorders." (PMID 38016492, 2024). "The pro-inflammatory cytokines involved in CRS, such as IL-6 and TNF-α, have been well implicated in the pathophysiology of mood and anxiety disorders, as inflammation is increasingly recognized as a contributor to psychiatric conditions." (PMID 40094890, 2025). "For instance, a meta-analysis revealed that IL-6 commonly increased in individuals with anxiety disorders compared to controls in most studies." (PMID 39757257, 2025). "IL-6 plays a complex and seemingly contradictory dual role in the relationship between anxiety disorders and gut microbiota." (PMID 41459223, 2025). "Previous studies have documented associations between inflammation and psychiatric symptoms, and elevated levels of IL-6 and CRP have been linked to greater symptom severity in various anxiety disorders." (PMID 39063640, 2024). "Some studies have shown that individuals with anxiety disorders also have higher levels of circulating IL-6 or higher levels of IL-6 gene expression." (PMID 38016492, 2024). "Consistent with this analysis, we found elevated levels of IL-1β, TNF-α, IL-6, and IL-4 expression among children with TD, whereas state anxiety among those children correlated positively with IL-17 levels." (PMID 38956051, 2024). "Additionally, physical activity reduces systemic inflammation by lowering pro-inflammatory cytokines (IL-6, TNF-α, CRP), which are linked to the onset and progression of anxiety disorders." (PMID 41246056, 2025). "Genetic analyses suggest that IL-6 signaling could be relevant for memory, and that the association between CRP and anxiety disorders could be causal." (PMID 38699368, 2024). "Genetic analyses suggest that IL-6 signaling could be relevant for memory, and that the association between CRP and anxiety disorders could be potentially causal." (PMID 38699368, 2024). "Proinflammatory cytokines, including IL-6 and TNF-α, have been implicated in the etiologies of clinical anxiety disorders, which may affect the IGF-1 concentration." (PMID 37151979, 2023). "Earlier studies demonstrated plasma IL-6 levels to be elevated in chronic stress, which may contribute to neurobehavioral complications, including anxiety disorders, and affect the brain phenotype in the offspring." (PMID 37840785, 2023). "Furthermore, patients with depressive or anxiety disorders exhibited increased levels of cytokines such as interleukin-6 (IL-6) and tumor necrosis factor-α (TNF-α)." (PMID 35705957, 2022). "In conclusion, the findings suggest that higher neuroticism, independent of diagnosis of current MDD or anxiety disorder, is associated with elevated levels of L/A ratio, leptin and IL-6 in young adults with and without psychiatric co-morbidity." (PMID 33963214, 2021).
anxiety disorder (continued). "Reports have shown that cytokines such as interleukin (IL)-6, tumor necrosis factor-alpha (TNF-α), IL-10, and monocyte chemoattractant protein-1/CCL2 might be well associated with depressive, bipolar, or anxiety disorders." (PMID 29740354, 2018). "Therefore, corticosterone is utilized as a marker for assessing stress in studies of humans and animals alike; additionally, elevated levels of pro-inflammatory cytokines such as TNF-α, IL-1β, and IL-6 may serve as biological markers of anxiety disorders." (PMID 33628177, 2020). "In the high-dose group correlation analyses corrected for 8 comparisons revealed a negative association between changes in IL-6 levels and positive mood (r = −.654, p<0.01), calmness (r = −.654, p<0.01) as well as a positive correlation between IL-6 and state anxiety (r = .762, p<0.005)." (PMID 22164271, 2011). "↑ in patients with GAD compared with controls in unadjusted data obtained from author, but ↔ between IL-6 and GAD compared with other anxiety disorders." (PMID 31326932, 2019). "This suggests that CORT, inflammatory factors (IL-6, IL-1β, CD86, TNF-α, TGF-β, IL-10), 5-HT, and GABA may serve as biomarkers for anxiety disorders." (PMID 40078708, 2025). "In individuals with current depressive or anxiety disorders compared to healthy controls, elevated levels were observed in CRP, IL-6, IL-8, IL-18, MCP-1, MIP-1α, MIP-1β, MMP2, and TNF-β, while TNF-α, IL-10, IFN-γ, IL-2, and IL-4 levels either showed no significant elevation or were lower." (PMID 39273641, 2024). "Higher levels of pro-inflammatory peripheral cytokines have been identified both in models of anxiety disorders (tumor necrosis factor-α [TNF-α] and interleukin [IL]-1 β, IL-6), as well as mood and anxiety disorders patients (c-reactive protein [CRP], TNF-alpha, IL-1, IL-6,)." (PMID 34680430, 2021). "Out of these biomarkers, neuroticism was positively associated with the L/A ratio, leptin and IL-6, independent of current diagnosis of MDD or anxiety disorder." (PMID 33963214, 2021). "Serum IL-6 concentrations are elevated after exercise, and IL-6 subsequently reaches the intestinal tract, leading to increased levels of Glucagon-like peptide-1(GLP-1) through stimulation of intestinal L-cells, which contribute to the relief of anxiety disorders and memory disorders." (PMID 41459223, 2025). "Recently, a metanalysis on 1077 anxiety disorders patients showed that, excluding patients with a chronic organic illness, moderately higher concentrations of pro-inflammatory markers (again mainly IL1-β, IL6, and TNF-alpha) were present in patients’ blood, compared to healthy controls." (PMID 34680430, 2021).